Y_RNA (Y RNA )
Gene: Miscellaneous RNA gene on chromosome Y (7,341,531 to 7,341,642, forward strand). Ensembl gene ENSG00000251996.
Homologues: Orthologues: chimpanzee Y_RNA (97% identical), macaque Y_RNA (86% identical). Paralogues in human: Y_RNA (88% identical), Y_RNA (81% identical), RNY1 (80% identical), Y_RNA (79% identical), RNY1P11 (78% identical), Y_RNA (78% identical), Y_RNA (77% identical), Y_RNA (76% identical), Y_RNA (75% identical), Y_RNA (74% identical), RNY1P2 (73% identical), Y_RNA (73% identical), and 93 more.